CLDN8 (claudin 8)
Diseases named in the same sentence as CLDN8 in open-access papers (continued):
Sharing a sentence is not in itself a finding about the gene and the disease.
infection (9 papers, 2020 to 2025). The state of being infected such as from the introduction of a foreign agent such as serum, vaccine, antigenic substance or organism. "During infection, this secreted protease cleaves the tumour suppressor E-cadherin in the adherens cell-to-cell junctions as well as claudin-8 and occludin in the tight junctions, which causes severe damage in the infected gastric epithelium." (PMID 37183214, 2023). "EgPSC infection also caused the upregulation of Cgn, Epb41, Cldn8, Shroom3, Cask, Rab3b, Epb41l2, Csnk2b, Prkcb, and MyI12a." (PMID 36713407, 2022). "The CLDN8 expression and TJs barrier function are attenuated by the infection of human colonic epithelial HT-29/B6 cells to Arcobacter butzleri or Campylobacter concisus, which are pathogenic bacteria causing diarrhea." (PMID 36986076, 2023). "Experiments are currently underway in our lab investigating the importance of the L/S171 mutation in HtrA-mediated cleavage of cell junction proteins occludin, claudin-8 and E-cadherin during infection." (PMID 37183214, 2023). "The similar expression trends of the genes were observed, as EgPSC infection upregulated the mRNA levels of Cldn8, and downregulated the mRNA levels of Pklr, Cldn4 and Cxcl12." (PMID 36713407, 2022). "For example, several classic tight junction related genes (Ocln and Cldn4) were significantly downregulated post-infection, whereas other tight junctions-relative genes (Cldn8, Epb41L2, Prkcb, and Shroom3) were upregulated." (PMID 36713407, 2022). "After 12-h infection, immunoblotting was applied by using α-claudin-8, α-HtrA and α-GAPDH antibodies." (PMID 33364202, 2020). "In contrast, infection of T84 cells with wt C. jejuni or the wt complemented strain led to a significant drop of fluorescence intensity of occludin and claudin-8 in the cellular tight junctions." (PMID 33364202, 2020). "After infection of T84 cells with wt C. jejuni, the fluorescence intensity of occludin and claudin-8 at the cell periphery was significantly reduced." (PMID 33364202, 2020). "The present results shown here demonstrate that HtrA from C. jejuni can cleave another major tight junction protein, claudin-8, as this has been shown both in vitro with purified proteins and upon infection of cultured polarized Caco-2 and T84 cells in vivo." (PMID 33364202, 2020). "In H. pylori, a functional HtrA is able to cleave components of the epithelial intercellular junction, such as E-cadherin and claudin-8, favoring the crossing of the epithelial barrier upon infection." (PMID 33260771, 2020). "Based on these immunofluorescence experiments, we can conclude that HtrA is involved in the disturbance of claudin-8 and its translocation from tight junctions into the cytoplasm during infection with C. jejuni." (PMID 33364202, 2020). "In contrast, infection with wt C. jejuni or the wt complemented strain (ΔhtrA/htrAwt) led to the disruption of both occludin and claudin-8 in tight junctions along with their appearance in the cytoplasmic area (white arrows)." (PMID 33364202, 2020). "At the peak of the infection, genes related to antimicrobial defense and barrier function, including Reg3a, Reg3g, Defb37, Defb40, Claudin-8, and Claudin-15, also showed altered expression, suggesting weakened antimicrobial protection and impaired tight junction integrity." (PMID 40630939, 2025). "Since infection by C. jejuni expressing intact HtrA leads to disorganisation of claudin-8 in Caco-2 cells, we came into assumption that HtrA might have a specific proteolytic activity against claudin-8." (PMID 33364202, 2020). "The results presented here suggest that claudin-8 is a major novel cleavage target for C. jejuni HtrA, and besides occludin, the second target protein in the tight junctions, which may help the pathogen to disrupt the epithelial barrier during infection." (PMID 33364202, 2020).
infection (continued). "Importantly, secretion of HtrA by the bacteria during infection in vivo or experiments with the recombinant proteins in vitro resulted in cleavage of the epithelial cell junction components E-cadherin, occludin, and claudin-8, which opens the tight and adherens junctions, respectively." (PMID 37183214, 2023). "Compared to mock-infected groups, Claudin 1 (CLDN1) and CLDN4 were significantly upregulated, while CLDN8 and Occludin (OCLN) were downregulated in the HP-PRRSV infection group." (PMID 35336858, 2022). "After 12 h of infection, Caco-2 cells were fixed in PFA and immunostained with antibodies against claudin-8 and C. jejuni as labelled with green and red fluorophores, respectively." (PMID 33364202, 2020). "The mean fluorescence of cytosolic claudin-8 upon infection did not change significantly within overall cell populations." (PMID 33364202, 2020). "Western blotting of protein samples from infected vs. uninfected cells revealed that an 18-kDa carboxy-terminal fragment is cleaved-off from the 26-kDa full-length claudin-8 protein, but not during infection with the isogenic ΔhtrA mutant." (PMID 33364202, 2020). "Wild-type C. jejuni induced the downregulation of claudin-8 signals in the tight junctions and an accumulation of claudin-8 agglomerates in the cytoplasm, which were not seen during infection with isogenic ΔhtrA knockout deletion or protease-inactive S197A point mutants." (PMID 33364202, 2020). "In addition, infection with whole Gram-negative bacteria revealed a significant increase in all analysed TJ proteins in Alpk1−/− organoids, while RNA expression levels of Tjp1 and Cldn8 were decreased." (PMID 32076438, 2020).
cancer (8 papers, 2014 to 2025). A tumor composed of atypical neoplastic, often pleomorphic cells that invade other tissues. "This stark contrast in the HER2+/ER− SKBR-3 mirrors the clinical observation that high CLDN8 expression is linked to poor chemo-response in HER2-driven cancer; when CLDN8 is removed, the cells succumb much more readily to the taxane." (PMID 40508219, 2025). "In other cancers, CLDN8 suppresses EMT and invasiveness via the AKT pathway, meaning its loss leads to a more mesenchymal, chemosensitive state." (PMID 40508219, 2025). "There are some reports concerning the downregulation of CLDN8 expression in cancer cells by miRNAs including miR-223, miR-361-5p, or miR-340-5p." (PMID 36986076, 2023). "Interestingly, high Cldn8 expression has been observed in clinical cancer cell samples relative to benign controls and was shown to promote a pro-migratory and proliferative phenotype in multiple studies which is in line with the more proliferative phenotype observed in oral epithelium." (PMID 32340108, 2020).
skin disorder (1 paper, 2025). Any deviation from the normal structure or function of the skin or subcutaneous tissue that is manifested by a characteristic set of symptoms and signs. "Central to our findings is the dysregulation of CLDN8, a key component of tight junctions, and hsa-miR-31-3p, a microRNA with emerging significance in skin disorders." (PMID 40160514, 2025).
CLDN8 also shares sentences with these, for which no sentence is quoted: colon adenocarcinoma (2 papers); inflammatory bowel disease (2); Renal oncocytoma (2); adenoma (1); amyotrophic lateral sclerosis type 1 (1); atopic dermatitis (1); autism (1); chromophobe renal cell carcinoma (1); collagenous colitis (1); hepatitis C (1); hepatocellular carcinoma (1); human papillomavirus infection (1); hydronephrosis (1); metastasis (1); prostate intraepithelial neoplasia (1); Sepsis (1); Yersinia enterocolitica infection (1).